MED8 (mediator complex subunit 8)
Description:
Component of the Mediator complex, a coactivator involved in the regulated transcription of nearly all RNA polymerase II-dependent genes. Mediator functions as a bridge to convey information from gene-specific regulatory proteins to the basal RNA polymerase II transcription machinery. Mediator is recruited to promoters by direct interactions with regulatory proteins and serves as a scaffold for the assembly of a functional preinitiation complex with RNA polymerase II and the general transcription factors. May play a role as a target recruitment subunit in E3 ubiquitin-protein ligase complexes and thus in ubiquitination and subsequent proteasomal degradation of target proteins.
Synonyms: ARC32; MGC17544; MGC19641
Tractability: Small molecule: a structure with a bound ligand is known. PROTAC: ubiquitination databases record sites on it; its protein half-life has been measured.
Gene: Protein-coding gene on chromosome 1 (43,383,917 to 43,389,808, reverse strand). Ensembl gene ENSG00000159479.
Subcellular location: Nucleus
Subcellular location (Human Protein Atlas): Nucleoplasm; Golgi apparatus
Pathways (Reactome):
Developmental Biology: Transcriptional regulation of white adipocyte differentiation
Disease: RSV-host interactions
Gene expression (Transcription): Generic Transcription Pathway
Metabolism: PPARA activates gene expression
Gene Ontology:
Molecular function: protein binding; RNA polymerase II cis-regulatory region sequence-specific DNA binding; transcription coregulator activity; ubiquitin protein ligase activity
Biological process: positive regulation of transcription elongation by RNA polymerase II; positive regulation of transcription initiation by RNA polymerase II; regulation of transcription by RNA polymerase II; RNA polymerase II preinitiation complex assembly; protein ubiquitination
Cellular component: core mediator complex; mediator complex; nucleus; nucleoplasm; ubiquitin ligase complex
Genetic constraint (gnomAD): Loss-of-function variants: 22 observed, 35.3 expected, observed/expected ratio (o/e) 0.62, 90% interval 0.44 to 0.89. The upper end of that interval is the gene's LOEUF score, 0.89, which puts it in group 3 of 6, group 1 being the genes least tolerant of losing a copy. Missense variants: 260 observed, 329.85 expected, observed/expected ratio (o/e) 0.79, 90% interval 0.71 to 0.87. Synonymous variants: 105 observed, 123.68 expected, observed/expected ratio (o/e) 0.85, 90% interval 0.72 to 1.
Homologues: Orthologues: chimpanzee MED8 (99% identical), macaque MED8 (99% identical), pig MED8 (97% identical), rat Med8 (97% identical), dog MED8 (97% identical), guinea pig MED8 (97% identical), rabbit MED8 (97% identical), mouse Med8 (97% identical), tropical clawed frog med8 (78% identical), zebrafish med8 (68% identical), Drosophila melanogaster MED8 (41% identical), rabbit MED8 (41% identical), and 1 more.
Diseases named in the same sentence as MED8 in open-access papers:
MED8 is named in the same sentence as 19 diseases in open-access papers, as found by Europe PMC text mining. Sharing a sentence is not in itself a finding about the gene and the disease. The quoted sentences say what the papers report.
renal cell carcinoma (4 papers, 2016 to 2023). "Other MED genes such as MED8 were found to associate with renal cell carcinoma, while MED12 associates with lung cancer." (PMID 37511575, 2023). "Differential expression of MED8 in renal cell carcinoma (RCC) and MED12 in lung cancer (LCa) were validated and further investigated by immunohistochemical staining on tissue microarrays containing large numbers of specimen." (PMID 27050271, 2016). "Upon closer examination of the individual subunits, for MED8, a subunit of the head module, high overexpression rates in ovarian (71%, n = 586/820), lung (47%, n = 226/483), bladder cancer (100%, n = 109/109) and renal cell carcinoma (20%, 10/50) were found." (PMID 27050271, 2016). "The mediator complex subunit 8 (MED8) is a major polymerase regulator and has been described as an oncogene in renal cell carcinoma, but its pathophysiological significance of HCC and its contribution to the prognosis of HCC remain unclear." (PMID 35558516, 2022).
colon cancer (2 papers, 2010 to 2016). "Our genome-wide strategy to identify immunogenic NMD-resistant transcripts has identified five novel cMS mutations (SFRS12IP1, MED8, ASXL1, FBXL3, RGS12) in at least 45% of eleven MSI-High colon cancer cell lines tested." (PMID 21209843, 2010). "However, as we were not able to detect any over- or underexpression on the transcriptional level in colon cancer, we decided to validate MED8 expression on the protein level in RCC, for which no previous data was available." (PMID 27050271, 2016).
atherosclerosis (1 paper, 2024). A disease characterized by the build-up of fatty material and calcium deposition in the arterial wall resulting in partial or complete occlusion of the arterial lumen. "In genetically predicted levels, higher expression of ANXA5, CCDC71L, MED8, MRAS, MRPS6, NTAN1, and SLA5A3 was positively associated with atherosclerosis risk." (PMID 39766313, 2024).
breast carcinoma (1 paper, 2022). "For example, the PKMYT1 is negatively correlated with the other 13 genes in breast cancer data, and MED8 is positively correlated with the other four genes." (PMID 36551179, 2022).
colorectal cancer (1 paper, 2016). A primary or metastatic malignant neoplasm that affects the colon or rectum. "In cancer, only the presence of MED8 mutations in colorectal cancer cell lines has been described." (PMID 27050271, 2016).
kidney cancer (1 paper, 2016). Primary or metastatic malignant neoplasm involving the kidney. "In kidney cancer, MED8 showed an overexpression in 20% (n = 10/50) of all samples." (PMID 27050271, 2016).
leiomyoma (1 paper, 2024). A well-circumscribed benign smooth muscle neoplasm characterized by the presence of spindle cells with cigar-shaped nuclei, interlacing fascicles, and a whorled pattern. "MED12 mutation-negative leiomyomas display copy number alterations in several other mediator complex subunits, such as MED18, MED8, CDK8, and the long non-coding RNA, RNA340 (CASC15)." (PMID 38279317, 2024).
liver cancer (1 paper, 2025). An epithelial or non-epithelial malignant neoplasm that arises from the liver. "Our study revealed significantly increased MED8 gene expression levels in HCC tissues, suggesting that targeting MED8 gene expression may modulate liver cancer development." (PMID 40377731, 2025).
schizophrenia (1 paper, 2020). A major psychotic disorder characterized by abnormalities in the perception or expression of reality. "Moreover, decreased expression of Mediator complex subunit 8 (MED8) was associated with both schizophrenia and ADHD." (PMID 32398653, 2020). "Further, we replicated the observed pleiotropic downregulation of MED8 in schizophrenia and ADHD, while the previous study demonstrated this association with ADHD was also significant using adrenal gland tissue." (PMID 32398653, 2020).
cancer (4 papers, 2008 to 2024). A tumor composed of atypical neoplastic, often pleomorphic cells that invade other tissues. "Further investigation has elucidated that MED8 plays a crucial role in determining a poor prognosis in HCC, principally by promoting cancer progression through the activation of TH2 cytokines." (PMID 38238845, 2024).
tumor (3 papers, 2016 to 2026). "In this, MED8 was found to significantly associate with outcome related parameters of tumor severity such as lymphnode status, distant metastases and T stage." (PMID 27050271, 2016). "The mRNA expression of MED8 was significantly elevated in TCGA-LIHC tissues relative to the adjacent non-tumor liver tissues." (PMID 35558516, 2022). "MED8 was essential for tumor proliferation and survival both in vitro and in vivo." (PMID 42157323, 2026). "The dysregulation of these pathways causes tumor progression in HCC, which could explain why the link of high MED8 expression was linked to advanced clinicopathological parameters." (PMID 35558516, 2022). "In conclusion, MED8 might serve as a potential target in patients suffering from ccRCC to counteract tumor growth and metastatic spread." (PMID 27050271, 2016). "Since MED8 expression could influence the proportion of tumor-infiltrating immune cells in HCC by Estimating Relative Subsets of RNA Transcripts (CIBERSORT) analysis; the MED8-related immunomodulators were subsequently identified from the TISIDB website." (PMID 35558516, 2022).
infection (2 papers, 2010 to 2017). The state of being infected such as from the introduction of a foreign agent such as serum, vaccine, antigenic substance or organism. "Strikingly, despite encoding an NSs protein that contains the Med8 interaction domain, mBUNNSs22 fails to block RNA polymerase II activity during infection." (PMID 20427562, 2010). "Therefore, the interaction between the NSs C terminus and Med8, though essential, seems not to be sufficient to block phosphorylation of CTD-Ser2 or to promote degradation of RNAPII during infection." (PMID 20427562, 2010).
neurological disorders (1 paper, 2025). "While MED8’s role in neurological diseases has been suggested in preclinical studies, the specific mechanisms and clinical consequences underlying the involvement of SZT2/MED8’s interaction remain areas for further investigation." (PMID 41465117, 2025). "The possible implication of MED8 in neurological diseases has been suggested by its relationship with the Seizure Threshold 2 gene (SZT2) (MIM *615463), whose mutations are related to epileptic encephalopathy and intellectual disability." (PMID 41465117, 2025).
MED8 also shares sentences with these, for which no sentence is quoted: lung carcinoma (2 papers); bladder cancer (1); glioma (1); Hematological Disease (1); neurodegenerative disease (1); ovarian carcinoma (1).